TGIF2 (TGFB induced factor homeobox 2)
Description:
Transcriptional repressor, which probably repress transcription by binding directly the 5'-CTGTCAA-3' DNA sequence or by interacting with TGF-beta activated SMAD proteins. Probably represses transcription via the recruitment of histone deacetylase proteins.
Tractability: PROTAC: ubiquitination databases record sites on it.
Gene: Protein-coding gene on chromosome 20 (36,571,894 to 36,593,950, forward strand). Ensembl gene ENSG00000118707.
Subcellular location: Nucleus
Subcellular location (Human Protein Atlas): Nucleoplasm; Centrosome
Pathways (Reactome):
Signal Transduction: Downregulation of SMAD2/3:SMAD4 transcriptional activity; SMAD2/SMAD3:SMAD4 heterotrimer regulates transcription
Cell-Cell communication: Negative Regulation of CDH1 Gene Transcription
Gene Ontology:
Molecular function: sequence-specific double-stranded DNA binding; DNA-binding transcription factor activity; DNA-binding transcription factor activity, RNA polymerase II-specific; DNA-binding transcription repressor activity, RNA polymerase II-specific; RNA polymerase II cis-regulatory region sequence-specific DNA binding; DNA binding
Biological process: negative regulation of transcription by RNA polymerase II; regulation of DNA-templated transcription
Cellular component: nucleoplasm; chromatin; nucleus
Genetic constraint (gnomAD): Loss-of-function variants: 5 observed, 15.76 expected, observed/expected ratio (o/e) 0.32, 90% interval 0.17 to 0.67. The upper end of that interval is the gene's LOEUF score, 0.67, which puts it in group 2 of 6, group 1 being the genes least tolerant of losing a copy. Missense variants: 264 observed, 307.84 expected, observed/expected ratio (o/e) 0.86, 90% interval 0.77 to 0.95. Synonymous variants: 131 observed, 129.2 expected, observed/expected ratio (o/e) 1.01, 90% interval 0.88 to 1.17.
Homologues: Orthologues: chimpanzee TGIF2 (100% identical), macaque TGIF2 (99% identical), dog TGIF2 (97% identical), guinea pig TGIF2 (95% identical), rabbit TGIF2 (95% identical), rat Tgif2 (95% identical), pig TGIF2 (94% identical), rat AABR07027925.2 (94% identical), mouse Tgif2 (94% identical), tropical clawed frog tgif2 (50% identical), Drosophila melanogaster achi (37% identical), Drosophila melanogaster vis (37% identical), and 5 more. Paralogues in human: TGIF1 (50% identical), TGIF2LX (37% identical), TGIF2LY (26% identical), MEIS2 (23% identical), MEIS3 (21% identical), PKNOX1 (20% identical), MEIS3P2 (20% identical), PKNOX2 (19% identical), MEIS1 (18% identical), PBX3 (16% identical), PBX2 (16% identical), PBX1 (15% identical), and 1 more.
Diseases named in the same sentence as TGIF2 in open-access papers:
TGIF2 is named in the same sentence as 55 diseases in open-access papers, as found by Europe PMC text mining. Sharing a sentence is not in itself a finding about the gene and the disease. The quoted sentences say what the papers report.
colon cancer (10 papers, 2015 to 2025). "Increased TGIF2 protein levels have been implicated in many cancers, including ovarian, esophageal, lung, and colon cancer, which implies that TGIF2 might be involved in cell proliferation." (PMID 34965271, 2021). "In colon cancer, TGIF2 was reported to interact with PKM2 to recruit HDAC3 to the E-cadherin promoter, leading to EMT upon EGF stimulation." (PMID 31871777, 2019). "In colon cancer cells, TGIF2 directly interacts with PKM2 in the nucleus by EMT stimulation, and recruits histone deacetylase 3 to the CDH1 (E-cadherin) promoter sequence, which subsequently deacetylates histone H3 and suppresses CDH1 transcription." (PMID 30333907, 2018). "TGIF2 has been reported to interact with PKM2 and recruit HDAC3 to the E-cadherin promoter, promoting EMT in colon cancer." (PMID 36647029, 2023). "The transcriptional activity of PKM2 was also reported in colon cancer, showing that PKM2 interacted with TGIF2 to transcriptionally regulated TGF-β signaling." (PMID 25788265, 2015). "In colon cancer, BMP7 is common overregulated gene, as are TGFB2, TGFBI, and TGIF2, which might be involved in the regulation of SOX4." (PMID 39228892, 2024). "Moreover, in colon cancer cells, PKM2 interacts with TGFβ-induced factor homeobox 2 (TGIF2) during TGFβ-induced EMT." (PMID 31822964, 2020).
lung adenocarcinoma (8 papers, 2019 to 2024). A carcinoma that arises from the lung and is characterized by the presence of malignant glandular epithelial cells. "Phosphorylated transforming growth factor beta (TGF-β)-induced factor homeobox 2 (TGIF2) can induce epithelial–mesenchymal transition (EMT) and metastasis of lung adenocarcinoma, and p-TGIF2 is a potential therapeutic target for lung adenocarcinoma metastasis." (PMID 37675097, 2023). "In the present study, we investigated the function and mechanism of TGIF2 in promoting the progression of lung adenocarcinoma (LUAD) in vitro and in vivo." (PMID 31871777, 2019). "Here, we report that TGIF2 mediates the EGFR–RAS–ERK signaling pathway to enhance the stemness of lung adenocarcinoma (LUAD) cells and, therefore, promote the progression and metastasis of LUAD." (PMID 31871777, 2019). "Compared with squamous cell carcinoma (n = 24) and large-cell undifferentiated carcinoma (n = 12), lung adenocarcinoma (n = 24) showed even higher TGIF2 expression (P < 0.001)." (PMID 31871777, 2019). "TGF-β-induced factor homeobox 2 (TGIF2) phosphorylation triggered the EGFR–RAS–ERK signaling pathway to enhance the stemness of lung adenocarcinoma cells, thus promoting its progression; by silencing TGIF2, there is a decrease of cancer stem cell-like properties in NSCLC cells." (PMID 37190223, 2023). "TGIF2 has been identified as an oncogene in some cancers, such as lung adenocarcinoma and glioma." (PMID 32709240, 2020). "In lung cancer, TGIF2 has been found to mediate the EGFR-RAS-ERK signaling pathway, enhancing the stemness of lung adenocarcinoma cells and facilitating LUAD progression and metastasis." (PMID 38629068, 2024). "Here, we investigated the roles of p-TGIF2 in promoting epithelial–mesenchymal transition (EMT) and metastasis in lung adenocarcinoma (LUAD)." (PMID 36647029, 2023). "CTCF, MLLT1, and TGIF2 are transcriptional regulators that play crucial roles in the transcription of important proto-oncogenes such as FOXM1, MYC, HoxA gene family, and OCT4 in multiple cancer types including HCC, esophageal cancer, and lung adenocarcinoma." (PMID 37335919, 2023). "In addition, we analyzed the correlation between the level of TGIF2 and the first progression (FP) and post progression survival (PPS) of patients with lung adenocarcinoma." (PMID 36647029, 2023).
glioma (7 papers, 2020 to 2025). A benign or malignant brain and spinal cord tumor that arises from glial cells (astrocytes, oligodendrocytes, ependymal cells). "Subsequently, we further delved into the association between TGIF2 expression levels and the infiltration levels of different immune cells in gliomas." (PMID 38629068, 2024). "Although this study demonstrated an association between TGIF2 and glioma, there are still some limitations and shortcomings of this study." (PMID 38629068, 2024). "Multivariate Cox regression analysis, after confounding with other clinicopathologic variables, identified TGIF2 as an independent prognostic risk factor for glioma patients (HR, 2.366; 95% CI, 1.620-3.455; p < 0.001)." (PMID 38629068, 2024). "FZD7, linked to glioma cell motility and invasiveness, aligns with our observation of TGIF2 promoting glioma cell migration." (PMID 38629068, 2024). "We established high TGIF2 expression as an independent risk factor for OS in glioma patients, as validated by multivariate Cox regression analysis." (PMID 38629068, 2024). "High expression of TGIF2 was associated with malignant phenotypes and poor prognosis in glioma patients, indicating its potential as an independent prognostic factor." (PMID 38629068, 2024). "TGIF2 emerges as a potential biomarker for glioma, possibly linked to tumor immune infiltration and EMT." (PMID 38629068, 2024). "The top 10 hub genes highlighted potential central regulators in the context of TGIF2-associated glioma biology." (PMID 38629068, 2024). "In this study, we focus on the transcription factor TGIF2 and propose for the first time its potential as a promising diagnostic and prognostic target for glioma." (PMID 38629068, 2024). "We investigated the association between TGIF2 expression and various clinicopathologic characteristics of glioma patients in the TCGA database." (PMID 38629068, 2024). "Notably, NOTCH signaling was reported to be associated with EMT, and the promotion of EMT in glioma cell by TGIF2 has been reported in glioma, speculating a potential regulatory crosstalk between TGIF2 and NOTCH signaling." (PMID 38629068, 2024). "CircMMP1 is up-regulated in glioma cells and tissues, and the circMMP1 knockdown reduced glioma progression and increased apoptosis and autophagy by targeting the miR-195-5p/TGIF2 axis." (PMID 39877636, 2025). "Next, we transfected the PX459-gRNA33 plasmid, which was effective in editing TGIF2, into glioma U251 cells, and screened for TGIF2 knockout cell lines using Sanger sequencing." (PMID 38629068, 2024). "The findings indicated a positive correlation between TGIF2 expression and most immunoregulatory genes, implying a potential role for TGIF2 in regulating glioma immune infiltration." (PMID 38629068, 2024). "The implications of these findings underscore the potential importance of TGIF2 in shaping the glioma immune microenvironment." (PMID 38629068, 2024). "To unravel the intricate relationship between TGIF2 expression and the tumor immune response in glioma, we meticulously analyzed the disparities in the glioma immune microenvironment between high and low TGIF2 expression groups." (PMID 38629068, 2024). "In conclusion, our results suggest that TGIF2 can be used as a promising new indicator for predicting the malignant phenotypes and clinical prognosis of glioma patients, and correlates with immune infiltration and EMT phenotype." (PMID 38629068, 2024). "The expression of TGIF2 in various human normal tissues, normal brain tissues, and gliomas was investigated using HPA, TCGA, GTEx, and GEO databases." (PMID 38629068, 2024). "Collectively, these results suggest a potential co-regulation of migration and invasion in glioma by TGIF2 and these identified hub genes." (PMID 38629068, 2024).
glioma (continued). "Subcellular localization of TGIF2 protein is predominantly in the nucleus in the human glioma cell line SH-SY5Y." (PMID 38629068, 2024). "In summary, this comprehensive analysis not only revealed potential regulatory networks with TGIF2 in glioma but also highlighted a promising gene cluster for prognostic assessment." (PMID 38629068, 2024). "The outcomes unveiled a significant elevation in stromal scores, immunity scores, and estimated scores in glioma patients with high TGIF2 expression." (PMID 38629068, 2024). "The analysis of genes coexpressed with TGIF2 in glioma provided valuable insights into potential regulatory networks and prognostic markers." (PMID 38629068, 2024). "Kaplan-Meyer analysis demonstrated that glioma patients with high TGIF2 expression exhibited poor OS, DSS and PFI." (PMID 38629068, 2024). "Our investigation demonstrated that TGIF2 expression significantly surpasses normal tissue levels in gliomas and correlates with adverse prognosis and malignant phenotypes." (PMID 38629068, 2024). "These insights contribute to a deeper understanding of TGIF2’s impact on glioma development and progression." (PMID 38629068, 2024). "Our results revealed a significant overexpression of TGIF2 in gliomas compared to normal human brain tissues." (PMID 38629068, 2024). "For histological type, glioblastoma exhibited significantly higher TGIF2 expression compared to other glioma types." (PMID 38629068, 2024). "To further explore the relationship between TGIF2 and tumor immunity, we analyzed the infiltration level of immune cells in the microenvironment of glioma tumors." (PMID 38629068, 2024). "Hsa-miR-129-5p, a tumor suppressor, is down-regulated in gliomas and inhibits glioma proliferation, migration and development by targeting TGIF2, WNT5A, DNMT3A, HOXC10, FNDC3B." (PMID 35601497, 2022). "Ion channel and glutamate signaling are facilitators of glioma cell invasion and migration, yet they were negatively correlated with high TGIF2 expression, which may be related to glioma grading." (PMID 38629068, 2024). "We assessed the prognostic value of TGIF2 expression for glioma patients in the TCGA database." (PMID 38629068, 2024). "Integrating these hub genes with TGIF2 may enhance the accuracy of prognostic predictions in glioma patients." (PMID 38629068, 2024). "Additionally, in vitro experiments revealed that knockdown and knockout of TGIF2 inhibited glioma cell invasion, migration and suppressed the epithelial-mesenchymal transition (EMT) phenotype." (PMID 38629068, 2024). "In addition, combined with previous studies, our in vitro experiments have provided a preliminary exploration of the role of TGIF2 in glioma migration, invasion and EMT, and the specific mechanisms and more functions in glioma need to be further investigated." (PMID 38629068, 2024). "To further elucidate the biological function of TGIF2 in glioma development, we divided glioma patients into high and low expression groups based on the median TGIF2 expression, analyzed the differentially expressed genes in the two groups, and performed functional enrichment analysis." (PMID 38629068, 2024). "TGIF2 mRNA was found to be upregulated in 21 cancers, including glioma." (PMID 38629068, 2024). "Initially, we employed siRNA to knock down TGIF2 expression in the U251 glioma cell line." (PMID 38629068, 2024). "Moreover, elevated TGIF2 expression correlated with malignant phenotypes and poor prognosis in glioma patients, establishing it as a potential independent prognostic indicator." (PMID 38629068, 2024). "Furthermore, a comprehensive analysis of the TGIF2 coexpression gene network in glioma was conducted, shedding light on the expression patterns of genes interacting with TGIF2 and the potential clinical relevance of hub genes." (PMID 38629068, 2024).
glioma (continued). "For example, it had been found that the growth and migration of chondrosarcoma cells could be restrained by targeting SOX4 and inhibiting glioma cells’ proliferation by targeting TGIF2." (PMID 35456485, 2022). "TGIF2 induced the growth of glioma cells by promoting the cell cycle and inhibiting apoptosis." (PMID 34965271, 2021). "Furthermore, in vitro experiments were performed by knocking down and knocking out TGIF2 using siRNA and CRISPR/Cas9 gene editing, and the role of TGIF2 in glioma cell invasion and migration was analyzed using transwell assay, scratch wound-healing assay, RT-qPCR, and Western blot." (PMID 38629068, 2024). "However, whether TGIF2 can serve as a biomarker for tumor progression, diagnosis, and prognosis in glioma remains unclear." (PMID 38629068, 2024). "ECM-related functions, such as extracellular matrix organization, ECM receptor interaction, and collagens and laminin interactions, were enriched in the TGIF2 high-expression phenotype, suggesting involvement in ECM formation in glioma." (PMID 38629068, 2024). "Previous in vitro experiments have suggested that TGIF2 promotes the EMT phenotype and migration in U87MG and A172 glioma cells, indicating the potential involvement of TGIF2 in regulating glioma cell invasion and tumor metastasis." (PMID 38629068, 2024). "Next, we explored the relationship between TGIF2 and prognosis (OS, DSS, and PFI) across different clinicopathologic subgroups of glioma." (PMID 38629068, 2024). "A total of 699 patients’ clinicopathologic information was included in the statistics, and the chi-square test revealed that TGIF2 expression was significantly correlated with age, WHO grade, IDH status, 1p/19q codeletion, histological type, OS event, DSS event and PFI event in glioma patients." (PMID 38629068, 2024). "The positive correlation between the high expression of ECM and TGIF2 suggests that TGIF2 may be involved in the formation of the ECM and thus promote the migration and invasion of glioma cells." (PMID 38629068, 2024). "Finally, knockdown and knockout of TGIF2 inhibited invasion, migration and EMT of U251 cells in vitro, suggesting its potential function in glioma invasion and migration." (PMID 38629068, 2024). "TGIF2 expression increased with WHO grade classification, peaking in G4 glioma." (PMID 38629068, 2024).
ovarian carcinoma (5 papers, 2003 to 2021). A malignant neoplasm originating from the surface ovarian epithelium. "Previous research indicated that upregulated TGIF2 was restrained by restoration of miR-34c expression in HCC, while miR-148a interacted with TGIF2 and thereby moderated ovarian cancer cell proliferation and invasion." (PMID 34965271, 2021). "Amplification of 20q13 may be particularly heterogeneous as AURKA, TGIF2, PTPN1 and ZNF217, and ADRM1, and other genes, have been cited as drivers of 20q13 amplification in ovarian cancer." (PMID 19419571, 2009).
cervical cancer (4 papers, 2024 to 2025). A primary or metastatic malignant neoplasm involving the cervix. "However, TGIF2 is also heavily associated with cervical cancer metastasis." (PMID 38886487, 2024). "For instance, in cervical cancer, TGIF2 downregulates FCMR by binding directly to its promoter, thereby promoting cervical cancer metastasis." (PMID 38629068, 2024). "TGIF2 promotes a variety of YAPon cancers, such as ovarian and cervical cancer." (PMID 39172021, 2024).
lung carcinoma (4 papers, 2019 to 2025). "In lung cancer, TGIF2 phosphorylation is a therapeutic target that drives EMT and metastasis." (PMID 39781447, 2025). "We also analyzed the correlation between the level of TGIF2 and the relapse-free survival (RFS) of patients with lung cancer in previously generated microarray data sets from 2437 patients with LUAD." (PMID 31871777, 2019). "Likewise, CircCPA4 has been shown to absorb miR-214-3p, leading to elevated TGFB-induced factor homeobox 2 (TGIF2) expression and lung cancer development." (PMID 40191724, 2025). "Furthermore, TGIF2-positive staining was significantly correlated with E-cadherin-negative staining in human lung cancer specimens." (PMID 36647029, 2023).
osteoporosis (4 papers, 2016 to 2024). A condition of reduced bone mass, with decreased cortical thickness and a decrease in the number and size of the trabeculae of cancellous bone (but normal chemical composition), resulting in increased fracture incidence. "MiR-21 overexpression reversed osteoporosis by targeting RECK and miR-34a prevented osteoporosis by inhibiting osteoclastogenesis via targeting Tgif2." (PMID 28471397, 2017). "This miRNA targets TGIF2 in osteoclasts and NOTCH1 in osteoblasts to ameliorate both post-menopausal and senile osteoporosis." (PMID 39452495, 2024). "We believe that miR-34a blocks osteoporosis and BM by inhibiting osteoclastogenesis in HCC patients because miR-34a has been found to directly target transforming growth factor-β-induced factor 2 (TGIF2) and to reduce bone resorption." (PMID 27893432, 2016).
prostate carcinoma (4 papers, 2021 to 2024). A carcinoma that arises from epithelial cells of the prostate gland. "Circ_0063329 is significantly downregulated in prostate cancer cells and tissues, and it can inhibit the proliferation and metastasis of prostate cancer by modulating the miR-605-5p/TGIF2 axis." (PMID 38994627, 2024). "Importantly, miR-181a is identified as an oncogenic role in prostate cancer cells and prostate tumor samples, and miR-181a promotes epithelial to mesenchymal transition of prostate cancer cells by targeting TGIF2." (PMID 33648424, 2021).